KEAP1 (kelch like ECH associated protein 1)
Diseases named in the same sentence as KEAP1 in open-access papers (continued):
Sharing a sentence is not in itself a finding about the gene and the disease.
Parkinson disease (27 papers, 2010 to 2025). A progressive degenerative disorder of the central nervous system characterized by loss of dopamine producing neurons in the substantia nigra and the presence of Lewy bodies in the substantia nigra and locus coeruleus. "Dysfunction of the Nrf2/Keap1/p62 system has been associated with many neurodegenerative disorders, including Parkinson's disease (PD)." (PMID 34838592, 2022). "Here, we hypothesize that variation in NFE2L2 and KEAP1, the genes encoding the two major regulators of the phase II response, may affect the risk of Parkinson's disease." (PMID 20196834, 2010). "A broad range of Nrf2 activators that target Keap1 and disrupt the Nrf2-Keap1 complex have been tested for neurodegenerative diseases including Huntington’s, Parkinson’s, Alzheimer’s diseases, and multiple sclerosis with promising results." (PMID 36138817, 2022). "DJ-1 (gene; PARK7) a recessively inherited Parkinson's gene, prevents oxidative stress in a Nrf2-dependent manner by preventing Keap1-mediated ubiquitination." (PMID 35126058, 2021). "Moreover, it quercetin-modified ultrasmall Cu2-xSe nanoparticles can activate the Nrf2/Keap1/p62 signaling pathway in neurons, thereby improving the motor dysfunction in patients with Parkinson’s disease." (PMID 38556857, 2024). "Therefore, the pharmacological activation of the Keap1/Nrf2 system is expected to enhance astrocytic protective mechanisms against ROSs, leading to a novel therapeutic strategy for the treatment of Parkinson disease." (PMID 35052674, 2022). "KEAP1/NRF2 is recognized as the most prominent protective system against electrophilic and oxidative insults; the upregulation of key enzymes in the defense against toxicants implicated in Parkinson’s disease and other neurodegenerative conditions is noteworthy." (PMID 36978921, 2023). "In recent years, many Keap1–Nrf2 PPI inhibitors and GSK3β inhibitors have been reported for various indications, such as Alzheimer’s disease, cancers, Parkinson’s disease, kidney diseases, Acetaminophen (APAP)–induced liver injury, and ferroptosis." (PMID 36678511, 2022). "It has also been reported that BAI protects rat pheochromocytoma cells against 6-hydroxydopamine-induced neurotoxicity through the activation of Keap1/NRF2/HMOX1 pathway, indicating the potential use of BAI to prevent neurodegenerative diseases such as Parkinson’s disease." (PMID 32526964, 2020). "Dimethyl fumarate disrupts the interaction between Keap1 and Nfr2 by alkylating cysteine residues in Keap1, which results in Nrf2 translocation to the nucleus and activation of mitochondrial biogenesis in multiple sclerosis and MPTP-induced model of Parkinson’s disease." (PMID 31139208, 2019). "Noncovalent inhibitors of the Keap1–Nrf2 protein–protein interaction (PPI) have therapeutic potential in a range of disease states including neurodegenerative diseases (Parkinson's and Alzheimer's diseases), chronic obstructive pulmonary disease and various inflammatory conditions." (PMID 29927029, 2018).
Alzheimer disease (25 papers, 2014 to 2026). A progressive, neurodegenerative disease characterized by loss of function and death of nerve cells in several areas of the brain leading to loss of cognitive function such as memory and language. "The protein-protein interplay of Keap1-Nrf2 has been implicated in many neurodegenerative disorders, including Alzheimer's disease and PD." (PMID 33777321, 2021). "As in Alzheimer’s disease, although expression of Keap1 is unchanged, Keap1 is found associated with intracellular inclusions in spinal cord motor neurons, and Keap1 mRNA is elevated in the motor cortex of post-mortem amyotrophic lateral sclerosis brain." (PMID 28820437, 2017). "Anti-inflammatory/immunostimulation activities of Natural Compounds on NF-κB (nuclear factor kappa-light-chain-enhancer of activated B cells)/Keap1 (kelch-like ECH-associated protein)/Nrf2 (nuclear factor erythroid 2-related factor 2) pathways in Alzheimer’s Disease." (PMID 34341712, 2021). "Furthermore, we observed that the autophagy protein P62 disrupts the normal autophagy process by interacting with the Nrf2/Keap1 axis, leading to an accumulation of Tau, a protein associated with Alzheimer's disease (AD), ultimately resulting in neurodegeneration." (PMID 40913351, 2025). "How P62 modulates the KEAP1/NRF2 axis has been elucidated in Alzheimer’s disease, hypoxic–ischemic brain damage, and virus-induced ferroptosis in EBV-induced tumorigenesis." (PMID 41356483, 2025). "A study in the cellular model of Alzheimer’s disease showed that sulforaphane increased Nrf2 expression by decreasing Nrf2 promoter demethylation, so its role on Keap1 promoter is also a possibility." (PMID 35052660, 2022). "Overall, our in silico study identified compound 145398-61-4 as a novel Keap1-Nrf2 inhibitor, highlighting its potential as a lead candidate for developing treatments for Alzheimer's disease and other neurodegenerative disorders, such as amyotrophic lateral sclerosis and multiple sclerosis." (PMID 41628199, 2026). "In addition, the aggregation of p62 and Keap1 has been detected in many human tumor cells, and certain neurodegenerative diseases, such as Alzheimer’s disease (AD), Parkinson’s disease (PD), and amyotrophic lateral sclerosis (ALS)." (PMID 39203919, 2024). "The goal of this study was to understand more about Keap1 and its role in Alzheimer’s disease so that we could create better treatments." (PMID 36561895, 2022). "Finally, five drugs with the highest promise as Keap1 inhibitors in the fight against Alzheimer’s disease are offered." (PMID 36561895, 2022). "Therefore, we hypothesised that genetically reducing Keap1 levels to constitutively boost CncC activity could benefit C9orf72 phenotypes as has been seen in a Drosophila model of Alzheimer’s disease." (PMID 38906677, 2024). "A recent study in a mouse model of Alzheimer's disease demonstrated significantly reduced expression of the Nrf2 gene, decreased levels of the downstream antioxidant proteins (HO‐1 and GSH), and increased expression of the Keap1 gene." (PMID 40913351, 2025).
glioma (25 papers, 2015 to 2025). A benign or malignant brain and spinal cord tumor that arises from glial cells (astrocytes, oligodendrocytes, ependymal cells). "Nuclear factor (erythoid-derived)-like 2(Nrf2) overexpression or Kelch-like ECH associated protein 1(Keap1) knockdown can accelerate the growth of glioblastoma and promote the development of glioma cells." (PMID 35530363, 2022). "In glioma patients, the co-occurrent hypermethylation of KEAP1 and MGMT predicts a lower risk of progression for patients treated with radiotherapy and temozolomide." (PMID 31159323, 2019). "Importantly, the promoter region of KEAP1 has been reported to be hypermethylated in gliomas and is associated with poor prognosis." (PMID 37189700, 2023). "Moreover, KEAP1 point mutations were identified in several human cancers such as gastric (11.1%), liver (2–8%), colorectal (7.8%), prostate (1.3%), gallbladder (30.7%), ovarian (37%), glioma (1.7%), head and neck (42%), and clear renal cell carcinoma (4.7%)." (PMID 29643973, 2018). "There were 5 ferroptosis-associated genes (KEAP1, NFE2L2, NOX4, ATF4, ASCL4) that have been tested in human glioma with different research methods." (PMID 36627482, 2023). "It was also found that fostering Nrf2 expression and inhibiting Keap1 both increase the resistance to ferroptosis in glioma cells." (PMID 36072803, 2022). "Overexpression of Keap1 in glioma cells decreased their migratory and proliferative behaviors while knockdown of Keap1 increased this abrogating behavior." (PMID 34466284, 2021). "Western blot analysis revealed that xCT protein levels increased in Nrf2 OE and Keap1 knockdown glioma cells." (PMID 28805788, 2017). "We found that Nrf2 overexpression or Keap1 knockdown foster the malignancy of gliomas and accelerate progression of glioma cells." (PMID 28805788, 2017). "Nrf2 overexpression or Keap1 knockdown in glioma cells accelerate proliferation and oncogenic transformation." (PMID 28805788, 2017). "Cell growth assays revealed that Nrf2 OE and Keap1 KD gliomas were less sensitive to erastin and RSL3 compared to control cells." (PMID 28805788, 2017). "Promoter methylation of KEAP1 gene is found in malignant glioma and a strong inverse correlation is discovered between methylation levels and KEAP1 mRNA transcript in tumor tissue suggesting a reduced expression of KEAP1 in glioma." (PMID 25851054, 2015). "In gliomas, for instance, KEAP1 expression may be reduced in the infiltrative tumor edge compared with the tumor core, influencing ferroptosis resistance and the effectiveness of ferroptosis‐targeted therapies in these regions." (PMID 40919133, 2025). "HACE1, for instance, promotes malignant progression and radiotherapy resistance in glioma by competitively binding to NRF2 with KEAP1, thereby enhancing NRF2 stability and IRES‐dependent upregulation of NRF2 translation levels, leading to a significant decrease in intracellular ROS levels." (PMID 40583858, 2025). "Additionally, by suppressing VEGFR2/Nrf2/Keap1 activation and subsequent enhancement of ferroptosis, apatinib treatment significantly restrains the growth of glioma cells." (PMID 38347631, 2024). "Additionally, the decrease in Nrf2 and phosphorylated VEGFR2 and the increase in Keap1 in Apatinib-challenged glioma cells were abolished by the Nrf2 overexpression." (PMID 35602105, 2022). "Our study proved that treatment with apatinib could restrain proliferation of glioma cells through induction of ferroptosis via inhibiting the activation of VEGFR2/Nrf2/Keap1 pathway." (PMID 35602105, 2022). "Although no mutations in KEAP1 or NFE2L2 have been reported in tumours of the central nervous system, NRF2 is hyperactivated in a subset of glioma patients, whose tumours display a mesenchymal subtype." (PMID 33276631, 2020).
glioma (continued). "As expected, the high proliferation rates of Nrf2 OE and Keap1 KD could be confirmed by these experiments and Nrf2 OE and Keap1 KD gliomas showed almost four to five times higher cell growth in comparison to controls." (PMID 28805788, 2017). "In addition, Nrf2 overexpression or Keap1 knockdown could accelerate the proliferation and oncogenic transformation of glioma cells." (PMID 35602105, 2022). "Then, the Human Protein Atlas (HPA) database analysis also shows that KEAP1 and NFE2L2 expression is significantly higher in glioma tissues compared to normal tissues." (PMID 36627482, 2023). "Our results verify that KEAP1 and NFE2L2 display clearly higher expression in glioma (GBM and LGG) tissues than in adjacent normal tissues." (PMID 36627482, 2023). "Of note, p62/SQSTM1-mediated degradation of KEAP1 and NRF2 promotes in vitro glioma stem cell survival." (PMID 36707509, 2023). "In glioma models, KEAP1 knockout significantly enhances tumor cell ferroptosis resistance through NRF2–SLC7A11 axis activation, molecularly elucidating the tumor‐suppressive mechanisms of KEAP1." (PMID 40919133, 2025). "Notably, activation of the Nrf2/Keap1 pathway increases xCT (SLC7A11) expression and diminishes ferroptosis, thus facilitating glioma cell growth." (PMID 34098867, 2021). "When cells were immunoprecipitated with Keap1 and immunoblotted with Nrf-2 antibody, no obvious change was observed in Keap1/Nrf-2 interaction in GSCs and corresponding non-GSCs glioma cells." (PMID 26124081, 2015). "Keap1 protein expression in cytosol between GSCs and non-GSCs glioma cells showed no obvious change." (PMID 26124081, 2015). "In order to examine the possibility that changes in Nrf-2 protein expression in GSCs and non-GSCs glioma cells might be due to differences in Keap1/Nrf-2 interaction, co-immunoprecipitation was performed to examine Keap1/Nrf-2 interaction status." (PMID 26124081, 2015).
prostate carcinoma (24 papers, 2015 to 2024). A carcinoma that arises from epithelial cells of the prostate gland. "The inhibition of BRD4 reduces ROS production in prostate cancer cells, and this effect is associated with the Keap1/Nrf2 signalling pathway." (PMID 37699016, 2023). "Despite protective effects on cancer progression, studies have also demonstrated the carcinogenic role of KEAP1 mutations in various cancers such as gallbladder, prostate, liver, colorectal, lung, breast, and prostate cancers." (PMID 33808001, 2021). "Hypermethylation of the promoter region of KEAP1 was reported in several cancers, including lung and prostate cancer, causing down-regulation of Keap1 expression and accumulation of Nrf2." (PMID 31022969, 2019). "In prostate cancer, Zhang and colleagues showed that KEAP1 has loss-of-function mutations providing a therapeutic potential for Nrf2 targeting." (PMID 29719593, 2018). "Another study indicated that the induction of androgen-independent prostate cancer cell apoptosis by puerarin is associated with the suppression of the Keap1/Nrf2/ARE signaling pathway, and puerarin pretreatment resulted in an increase in Keap1 and decline in Nrf2, HO-1, and NQO1 protein expression." (PMID 35935578, 2022). "Analyzing the current literature, it was revealed that NRF2/KEAP1 signaling pathway can be modulated by natural and synthetic compounds in both in vivo and in vitro models of prostate cancer." (PMID 37296999, 2023). "In this review, we discussed the current literature regarding the role of natural and synthetic compounds in regulating NRF2/KEAP1 signaling pathway in prostate cancer." (PMID 37296999, 2023). "The NRF2/KEAP1 signaling pathway is a promising target in the treatment of prostate cancer since it plays an important role in prostate cancer onset, progression and treatment resistance." (PMID 37296999, 2023). "In this review, we analyzed the current literature regarding the role of natural and synthetic compounds in modulating NRF2/KEAP1 signaling pathway in prostate cancer." (PMID 37296999, 2023). "Overall, our in vitro results have demonstrated that ALA can affect two cellular pathways playing a significant role in the progression of prostate carcinoma: Nrf2/Keap1/p62 and autophagy machinery, as recently highlighted in the literature." (PMID 38069431, 2023). "Recently, it was reported that kurarinone activated Nrf2 by downregulation of the expression of KEAP1, leading to the expression of antioxidant enzymes, including HO-1 in human prostate cancer cells." (PMID 34445094, 2021). "Consequently, this process leads to Keap1 isolation, ultimately reducing the transcriptional activation of Nrf2-mediated antioxidant genes, which in turn facilitates prostate cancer progression." (PMID 39664581, 2024). "Thus, the NRF2/KEAP1 pathway is an emerging chemo- and radio-therapeutic target in several cancer types including prostate cancer." (PMID 37296999, 2023). "Moreover, parthenolide increased ROS levels causing the oxidation of thioredoxin (TrX) in a LNCaP, PC3 and Duke University 145 (DU145) prostate cancer cells leading to a TrX-dependent increase on the reduction in KEAP1." (PMID 37296999, 2023). "It is reported that EZH2 downregulation in lung cancer leads to the reduction of H3K27me3 at NRF2 promoter area and increases NRF2 transcription eventually, whereas SetD7 can activate the antioxidant NRF2/KEAP1 pathway by elevating H3K4 methylation in prostate cancer cells." (PMID 35754474, 2022). "In lung, colon, and prostate cancers, KEAP1 promoter was found to be significantly hypermethylated." (PMID 33808001, 2021). "Also, the epigenetic sensor BRD4 (bromodomain protein 4), an acetylated histone-binding protein implicated in transcriptional regulation, was found to regulate KEAP1 function in a model of prostate cancer." (PMID 31097977, 2019).
prostate carcinoma (continued). "Several other functions of Esrrb have also been discovered including alteration of energy balance, estrogen receptor and glucocorticoid receptor transcription function modulation, Keap1-Nrf2 signaling inhibition, and tumorigenesis in prostate cancer and endometrial adenocarcinoma." (PMID 26627478, 2015). "In this review, we analyzed the current literature regarding the role of natural and synthetic compounds on NRF2/KEAP1 pathway modulating ROS and/or NRF2 status in prostate cancer cells." (PMID 37296999, 2023). "Conversely, in LNCaP cells, ALA increased p62/SQSTM1 expression, most likely because in this prostate cancer cell line ALA does not affect the Nrf2/KEAP1/p62/SQSTM1 axis or the oxidative/redox balance system." (PMID 38069431, 2023). "Thus, BRD4 might represent a fine-tune modulator of the antioxidant response in prostate cancer by influencing the expression of HO-1 and interacting with the NRF2/KEAP1 network." (PMID 31097977, 2019).